APOA5 (apolipoprotein A5)
Diseases named in the same sentence as APOA5 in open-access papers (continued):
Sharing a sentence is not in itself a finding about the gene and the disease.
Obesity (continued). "Apolipoprotein A5 (APOA5) gene, located on chromosome 11 adjacent to APOA1/APOC3/APOA4 gene cluster with known functions in the metabolism of plasma lipids, also modulates the risk of obesity in a number of studies." (PMID 24903888, 2014). "Since adipocytes are the largest storage depot for energy in the form of TG within the LDs in humans, it is reasonable to speculate that apoA5 may also target to adipocytes and regulate intracellular TG storage, providing a potential therapeutic target for obesity." (PMID 30053818, 2018). "Furthermore, under hypertrophied and insulin resistant conditions, attenuated endocytosis of apoA5 by adipocytes may lead to excessive augmentation of TG storage and abnormal metabolism of adipocytes, which promotes the development of obesity." (PMID 30053818, 2018). "Furthermore, since adipocytes provide the largest storage depot for TG and play a crucial role in the development of obesity, we could infer that apoA5 also acts as a novel regulator to modulate TG storage in adipocytes." (PMID 30053818, 2018). "Consistently, lower plasma level of apoA5 was found in obese subjects and was inversely correlated with BMI in humans, suggesting that decreased plasma apoA5 levels may have correlation with pathophysiology of obesity." (PMID 30053818, 2018). "However, in Chinese children and adolescents, limited data are available about the effect of APOA5 variants on childhood obesity and obesity-associated dyslipidemia such as elevated non-HDL-C levels." (PMID 24903888, 2014). "Next, we compared lower TG levels via APOA5 and LPL variation with over 100 lipoprotein measurements in a combined sample from the Netherlands Epidemiology of Obesity study (N = 4,838) and the Oxford Biobank (N = 6,999)." (PMID 35278410, 2022). "In summary, the obtained results suggest that regions 8q22-24, 11q23-25, and 12q13-15 are very likely to contain genes like VPS13B, APOA5, ZPR1, BUD13, and FAIM2 that control obesity-related factors in Iranian families with MetS21,22,27,28,31,32." (PMID 33727680, 2021). "This miRNA has not been previously reported as associated with obesity, however among its targets are those involved in the pathogenesis of obesity-related complications, e.g., genes encoding interleukins (IL-6, IL-17B and IL-22), apolipoproteins (APOA5) and their receptors (APOBR)." (PMID 29280944, 2017). "Amongst other genes that link depression with obesity, melanin-concentrating hormone receptor 2 (MCHR2), proprotein convertase subtilisin/kexin type 9 (PCSK9), and apolipoprotein A5 (APOA5) may be mentioned, as genes involved in energy-related processes." (PMID 41375608, 2025). "Our study aimed to research the correlation between obesity and serum BMP1, NRG4, and ApoA5 levels." (PMID 39280566, 2024). "The selected features of the proposed classifier on the Set 1 were CETP TaqIB [rs708272], CETP A373P [rs5880], LPL D9N [rs1801177], ApoE, ABCAI R1587K [rs2230808], APOA5 C-1131T [rs662799], LPL HindIII [rs320], APOC3 SstI [rs5128], family history of obesity, and diabetes, and APOA1 MspI [rs2893157]." (PMID 30026888, 2018). "Additionally, numerous identified mQTL-SNPs cover previously identified GWAS loci for obesity, lipid and diabetes related traits e.g. POMC, GIPR, GRB10, FADS2, SORT1 and APOA5." (PMID 27322064, 2016). "A significant interaction between APOA5 56G allele and high consumption of total fat and saturated fatty acids (SFA) associated with obesity but not with lipid levels, was found in this study." (PMID 26365669, 2015).
hyperlipidemia (17 papers, 2010 to 2025). "Collectively, these results strongly advocate for A8 and A3/8 as promising therapeutic avenues, not only for specific genetic conditions such as APOA5 or CREBH deficiency but also for a broader patient population with hyperlipidemia." (PMID 38521668, 2024). "We showed transcription factor GATA4 preferentially binds the T allele of rs651821, the protective allele for hyperlipidemia, which promoted APOA5 expression in liver cells and individuals with the TT genotype of rs651821." (PMID 35046404, 2022). "Our results are in concordance with previous studies demonstrating that the haplotype APOA5*4 is associated with 16% higher TG levels in Taiwan Chinese and with familial combined hyperlipidemia in Hong Kong Chinese." (PMID 25313938, 2014). "A number of human APOA5 gene nucleotide polymorphisms (SNPs) have been investigated for a possible role in mediating genetic predisposition to hyperlipidemia." (PMID 20696075, 2010). "The APOA5 -1131 T>C polymorphism has been suggested as a possible genetic factor associated with hyperlipidemia." (PMID 20696075, 2010). "Mice with APOA5 deficiency develop hyperlipidemia with reduced post-heparin plasma LPL activity." (PMID 40806668, 2025). "The possible mechanisms of how fiber regulates the risk of MetS by APOA5 rs662799 and rs651821 could be explained by the benefits of fiber on hyperlipidemia and hyperglycemia according to genetic variants." (PMID 38581036, 2024). "Interestingly, it is of note that HFD intervention caused more severe combined hyperlipidemia in ApoA5-/- hamsters, but only mild atherosclerotic development was shown." (PMID 38505614, 2024). "Therefore, the single nucleotide polymorphism APOA5–1131 T > C was associated with hyperlipidemia, the C allele posing a risk factor for susceptibility to hyperlipidemia." (PMID 33836655, 2021). "Meta-analysis of the data indicated that the C allele of APOA5 1131 T > C, the A allele at APOA1-75 bp, the APOB XbaI T allele, and the ε2 and ε4 allele of APOE were each a risk factor for susceptibility for hyperlipidemia." (PMID 33836655, 2021). "Of the existing apolipoprotein candidate genes, researchers have correlated APOA1, APOA5, APOB, and APOE gene polymorphisms with hyperlipidemia." (PMID 33836655, 2021). "Meta-analysis of the data indicated that APOA5–1131 T > C, APOA1 -75 bp, APOB XbaI, and APOE gene polymorphisms were significantly associated with hyperlipidemia, with OR values of 1.996, 1.228, 1.444, and 1.710, respectively." (PMID 33836655, 2021). "Given its role in blood lipid metabolism, the APOA5 gene is considered a candidate gene for hyperlipidemia." (PMID 20696075, 2010). "We speculated that compared with the severe combined hyperlipidemia in ApoC2-/- hamsters, the relatively lower lipid levels were not sufficient to initiate the visible atherosclerotic lesions in ApoA5-/- hamsters." (PMID 38505614, 2024). "Collectively, this suggests a therapeutic model for the synergistic effect of APOA5 and GATA4 on TG level, which may help control an individual’s susceptibility to hyperlipidemia and other metabolic abnormalities." (PMID 35046404, 2022). "APOA5 (apolipoprotein A5) and hyperlipidemia: There are multiple lines of evidence linking APOA5 and hyperlipidemia." (PMID 36782330, 2023). "In summary, the results of the present meta-analysis revealed that the C allele of APOA5 1131 T > C, the A allele at APOA1-75 bp, the APOB XbaI T allele, and the ε2 and ε4 alleles of APOE may represent genetic risk factors for susceptibility for hyperlipidemia." (PMID 33836655, 2021). "After fed an HFD containing 20% fat, 0.5% cholesterol for 3 months, ApoA5-/- hamsters showed severe combined hyperlipidemia with triglyceride levels more than 25,000 mg/dL and total cholesterol levels higher than 4000 mg/dL, while HDL-C levels were still lower in ApoA5-/- hamsters than WT hamsters." (PMID 38505614, 2024).
hyperlipidemia (continued). "Two patients with other five family members were included in this study for DNA-sequences of hyperlipidemia-related genes (such as LPL, APOC2, APOA5, LMF1, and GPIHBP1) and 43 healthy individuals and 70 HTG subjects were included for the screening of LPL gene mutations." (PMID 24646025, 2014). "Moreover, overexpression of both NR1D1 and ApoA5 via AAV8 did not reverse severe hyperlipidemia and NASH in ApoA5-/- hamsters and fed an HFD (data not shown), raising a concern of gene therapy applied to patients with severe HTG due to ApoA5." (PMID 38505614, 2024).
type 2 diabetes (16 papers, 2005 to 2025). "In a controlled trial from Yonsei University, researchers assessed the impact of whole grains and legumes versus refined rice in relation to the APOA5 -1131C variant status of patients with impaired fasting glucose or newly diagnosed type 2 diabetes." (PMID 37836506, 2023). "We genotyped the APOA5 -1131 T > C polymorphism in 203 Korean individuals with IFG or new-onset type 2 diabetes for the TT (n = 91), TC (n = 98), and CC (n = 14) alleles." (PMID 24775272, 2014). "Among 203 Korean patients with IFG or new-onset type 2 diabetes, 91 were homozygous (TT) for the T allele, 98 were heterozygous for the C allele (TC), and 14 were homozygous (CC) for the C allele of the APOA5 -1131 T > C polymorphism." (PMID 24775272, 2014). "This study shows an effect of the APOA5 -1131 T > C polymorphism in patients with IFG or type 2 diabetes among the Korean population." (PMID 24775272, 2014). "Despite these limitations, we found that the APOA5 -1131 T > C polymorphism plays an important role in the metabolic response to a 3-year dietary intervention in patients with IFG or new-onset type 2 diabetes." (PMID 24775272, 2014). "Therefore, we studied the effects of a 3-year high-carbohydrate diet with whole grains and legumes on circulating levels of apo A-V and triglycerides in patients with IFG or new-onset type 2 diabetes as a function of the APOA5 -1131 T > C polymorphism." (PMID 24775272, 2014). "Therefore, we tested the effects of a 3-year dietary intervention on triglyceride and apo A-V levels in patients with impaired fasting glucose (IFG) or new-onset type 2 diabetes as a function of their APOA5 polymorphisms." (PMID 24775272, 2014). "The purpose of this study was to estimate the effects of a 3-year dietary intervention on age-related changes in triglyceride and apolipoprotein (apo A-V) levels in patients with impaired fasting glucose (IFG) or new-onset type 2 diabetes as a function of the APOA5 -1131 T > C polymorphism." (PMID 24775272, 2014). "Although APOC2 is a critical factor for LPL activity and APOA5 stabilized LPL‐APOC2 complex, the reports of circulating levels of APOC2 and APOA5 as biomarkers in patients with type 2 diabetes are scarce." (PMID 37448184, 2023). "We genotyped the APOA5 -1131 T > C in individuals with impaired fasting glucose (IFG) or newly diagnosed type 2 diabetes, who were randomly assigned to either a group ingesting whole grain and legume meals daily or a control group for 12 weeks." (PMID 24690159, 2014). "Several studies have investigated whether the polymorphism in the apolipoprotein A5 (APOA5) is associated with type 2 diabetes mellitus (T2DM) risk." (PMID 24586566, 2014). "Similarly, a Japanese study showed that, in male patients with type 2 diabetes, ApoA5 was also positively correlated with TG but negatively correlated in healthy controls." (PMID 35854768, 2022). "However, few studies have explored genetic variations in the APOA5 gene in individuals with type 2 diabetes." (PMID 24775272, 2014). "This study showed that the dietary intervention prevented an age-related increase in triglyceride levels in individuals with IFG or new-onset type 2 diabetes who possess the TT allele, but not the CT or CC allele, of the APOA5 -1131 T > C polymorphism." (PMID 24775272, 2014). "Whole-grain ingestion prevented the age-related increase in triglyceride levels in patients with IFG or new-onset type 2 diabetes who carried the TT allele but not the C allele of the APOA5 -1131 T > C polymorphism." (PMID 24775272, 2014). "Besides, a positive correlation between apoA5 and TG was also observed in patients with type 2 diabetes." (PMID 24016248, 2013).
diabetes (15 papers, 2012 to 2025). "A meta-analysis of 19 studies found that SNP rs662799 upstream of APOA5 is significantly associated with the incidence of diabetes among Asians." (PMID 35886029, 2022). "A study has indicated that one of APOA5 SNPs, − 1131 T > C (rs2075291) variant, affects TG and HDL levels; therefore, increases the risk of developing cardiovascular diseases and diabetes." (PMID 30606120, 2019). "A significant association of the SNP rs662799 in APOA5 genes with CAD was observed after adjustment of gender, age, smoking, diabetes, hypertension and lipid status." (PMID 29310573, 2018). "In conclusion, we identify significant associations between 4 SNPs (NLRP1 rs12150220, IL2RA rs11594656, CLEC16A rs725613 and APOA5 −1131T/C) and diabetes." (PMID 23922971, 2013). "Within a cross-sectional analysis, participants of the German Diabetes Study (n = 348) with mean T2D duration of 6 months were investigated for fasting serum lipid levels, ApoA5 and ApoE genotypes; food consumption frequencies were assessed by a food propensity questionnaire." (PMID 27677442, 2016). "Dietary fat intake has also been reported to modify the effect of ApoA5 on serum triglyceride concentrations among young individuals without diabetes." (PMID 27677442, 2016).
myocardial infarction (13 papers, 2015 to 2024). Gross necrosis of the myocardium, as a result of interruption of the blood supply to the area, as in coronary thrombosis. "In Italians, APOA5 is associated with TG leaves and acute myocardial infarction (MI)." (PMID 26309253, 2015). "Interestingly, a previous Italian study showed that APOA5-1131T > C may affect the risk of early-onset myocardial infarction (MI), with an odds ratio of 1.44 (CI: 1.23–1.69) per C allele." (PMID 30671483, 2018). "Furthermore, several independent studies have consistently indicated that APOA5 variants were significantly associated with the risk of myocardial infarction (MI)." (PMID 31836003, 2019). "In addition, an earlier study has shown a significant association between the APOA5 rs662799 SNP and increased risk of early-onset myocardial infarction even after adjusting for triglycerides, providing further evidence that this SNP may simultaneously affect other atherogenic lipids such as LDLc." (PMID 29695967, 2018). "Although a correlation between ApoA5 gene polymorphisms and cardiovascular diseases, such as hypertension, myocardial infarction, or stroke has been showed, previous studies have not focused on the underlying mechanism among blood vessels." (PMID 35941581, 2022). "It has been reported that a doubling of genetically elevated non-fasting triglyceride concentrations due to APOA5 genetic variants was associated with a 1.9-fold increased risk of myocardial infarction." (PMID 31054570, 2019).
atherosclerosis (12 papers, 2015 to 2025). A disease characterized by the build-up of fatty material and calcium deposition in the arterial wall resulting in partial or complete occlusion of the arterial lumen. "CELSR2, FN1, SPARCL1, APOE, LPA, APOA5, and TGFB1 exhibit causal associations with both atherosclerosis and four cardiovascular diseases, suggesting their potential as therapeutic targets for atherosclerosis." (PMID 40649979, 2025). "Further research investigated the genetic interaction between USF1 and APOA5, revealing their combined influence on lipid levels and atherosclerosis progression." (PMID 40507612, 2025). "Some mutated genes are related to atherosclerosis, such as FAAH, KALRN, ATP10D, CUBN, APOA5, and LRP1." (PMID 36071494, 2022). "Together, these results show that APOA5 plays a critical role in promoting TRL and RLP clearance, an effect associated with protection from atherosclerosis." (PMID 32849290, 2020). "Likewise, animal models convincingly show that increased clearance of TRLs and RLPs by LPL activation (achieved by inhibition of APOC3, ANGPTL3, or ANGPTL4 action, or increased APOA5) results in protection from atherosclerosis." (PMID 32849290, 2020). "Since the SNPs at 11q23.3 region harbouring apolipoprotein coding genes namely APOA1, APOC3, APOA4, APOA5 and regulatory genes BUD13, ZPR1, SIK3 were found to be associated with defective lipid metabolism, this region was thought to play an important role in atherosclerosis and CAD risk." (PMID 33298998, 2020). "The three most promising proteins (CELSR2, FN1, and SPARCL1) were identified as potential therapeutic targets for atherosclerosis, while APOE, LPA, APOA5, TGFB1, and AGER also hold potential as drug targets for the disease." (PMID 40649979, 2025). "The atherosclerosis phenotype of Apoa5−/− mice has not been reported." (PMID 32849290, 2020).
Hepatic steatosis (11 papers, 2017 to 2025). Steatosis is a term used to denote lipid accumulation within hepatocytes. "To further clarify the role of NR1D1 in hepatic steatosis caused by ApoA5 deficiency, we overexpressed NR1D1 in HepG2 cells after knocking down ApoA5 and treated with 500μM palmitic acid for 16 h." (PMID 38505614, 2024). "Our data demonstrate that ApoA5 deficiency promotes increased lipid accumulation by increasing hepatic lipid synthesis, then leading to hepatic steatosis in hamsters on chow diet." (PMID 38505614, 2024). "To explore the potential molecular mechanism by which ApoA5 deficiency leads to fatty liver disease, we further analyzed liver transcriptomics data and identified 25 genes with the same trend in the liver of hamsters fed chow diet and HFD." (PMID 38505614, 2024). "A recent study showed that Apoa5 knockout hamsters develop hepatic steatosis even on normal chow diet." (PMID 40855499, 2025). "In summary, we successfully generated an ApoA5-deficient hamster model targeted by CRISPR/cas9 gene editing, which showed severe HTG with low-grade inflammation, leading to hepatic steatosis under chow diet condition." (PMID 38505614, 2024). "Indeed, deletion of Apoa5 in hamsters led to hepatic steatosis even on a chow diet, and Apoa5 knockdown in mice resulted in increased cytokine markers of systemic inflammation, including IL-10, IL-6, and TNF-α." (PMID 41043689, 2025). "Corroborating with that the expression of miR-94 was decreased in the liver of HFD-fed mice beside an increase of Apoa5 that could, along with other factors, be responsible for the impairment of insulin sensitivity and liver steatosis observed in our study." (PMID 31885789, 2019). "Carriers of APOA5, GPIHBP1, or LMF1 variants exhibited intermediate TG levels (1800–2500 mg/dL) and substantial pancreatitis risk, whereas APOB and APOC3 variant carriers had milder TG elevations (500–1500 mg/dL) but were more frequently associated with hepatic steatosis and metabolic comorbidities." (PMID 41300829, 2025). "Deleting FGF21 from LSD1-LKO liver partially reversed the improved hepatic steatosis, likely due to the FGF21-dependent alteration of lipid uptake (Cd36) and secretion (ApoB, ApoA4, and ApoA5)." (PMID 34314389, 2021). "Moreover, restoration of hepatic ApoA5 or activation of UCP1 in brown adipose tissue (BAT) by cold exposure or CL316243 administration could significantly correct sHTG and hepatic steatosis in ApoA5-/- hamsters." (PMID 38505614, 2024).